RAC2 (Rac family small GTPase 2)
Diseases named in the same sentence as RAC2 in open-access papers (continued):
Sharing a sentence is not in itself a finding about the gene and the disease.
bacterial infection (7 papers, 2021 to 2025). "Dysregulation in RAC2 expression increases susceptibility to bacterial infections and impairment of neutrophil functions." (PMID 39273699, 2024). "These Rac2 mutants displayed similar defects as found in human patients with the Rac2 mutation, including neutrophilia due to reduced neutrophil egress from the blood and reduced recruitment of neutrophils to sterile injury or bacterial infection." (PMID 34557186, 2021). "A rare inhibitory Rac2 mutation has been described in a patient who presented with recurrent and severe bacterial infection; however, phagocytic capacity was not assessed directly and Rac2 is also implicated in granule translocation (section 7.4) and NADPH oxidase function." (PMID 36440666, 2023). "Whereas Class2 uniquely included pathways related to bacterial infections (e.g., E. coli, Salmonella) together with actin-cytoskeleton and T-cell modules (e.g., ACTB, PFN1, RAC2, PIK3CD, CD3D/CD3G, STING1, TRADD, CASP8, BCL2, HLA-F)." (PMID 41394852, 2025).
infectious disease (1 paper, 2024). A disorder directly resulting from the presence and activity of a microbial, viral, or parasitic agent in humans. "Rac2 is a leukocyte-specific Rac GTPase, and humans and mice with deficiencies in Rac2 are susceptible to infectious disease." (PMID 38168666, 2024).
inflammation (1 paper, 2024). Aberrant reaction of the microcirculation characterized by movement of fluid and leukocytes from the blood into extravascular tissues. "In peritoneal inflammation, RAC2 is also indispensable for the accumulation of macrophages with effective phagocytosis." (PMID 38540147, 2024).
intestinal disease (1 paper, 2013). "Importantly, the findings presented here speak to the possible contribution of variants in the RAC2 gene, which may affect RAC2 expression and/or function, on the development of intestinal disease in humans." (PMID 23613889, 2013).
kidney disease (1 paper, 2025). "However, current research on the relationship between ITGB2, RAC2, and kidney disease remains inadequate." (PMID 40369957, 2025).
lung (1 paper, 2017). "Previous studies have shown that disruption of the gene encoding Rac2 ameliorated bleomycin induced lung injury and significantly attenuated lung inflammation and injury in an immune complex-mediated acute lung injury model." (PMID 28817691, 2017).
RAC2 also shares sentences with these, for which no sentence is quoted: non-small cell lung carcinoma (3 papers); rheumatoid arthritis (3); cardiac hypertrophy (2); combined immunodeficiency (2); congestive heart failure (2); liver cancer (2); lymphoma (2); meningioma (2); systemic mastocytosis (2); abscesses (1); ANCA-associated vasculitis (1); autism (1); autoimmune disease (1); Autoimmunity (1); B-cell lymphoma (1); bipolar disorder (1); brain diseases (1); bronchiectasis (1); cardiovascular disease (1); channelopathy (1); cholestasis (1); Dyskinesia (1); epilepsy (1); Epstein-Barr virus infection (1); esophageal cancer (1); esophagitis (1); Evans syndrome (1); graft versus host disease (1); head and neck cancer (1); head and neck squamous cell carcinoma (1).
A further 32 diseases each share a sentence with RAC2 in 1 paper.